PCNA (proliferating cell nuclear antigen)
Diseases named in the same sentence as PCNA in open-access papers (continued):
Sharing a sentence is not in itself a finding about the gene and the disease.
tumor (continued). "Immunostaining showed that berberine significantly decreased PCNA (44.60 ± 2.88 vs 65.80 ± 3.27, by 32%) and Ki-67 (6.73 ± 2.16 vs 14.89 ± 2.75, by 55%) positive cells, suggesting that berberine inhibits tumor cell proliferation in Apcmin/+ mice." (PMID 24279644, 2013). "In HCT-116 xenografts, we observed only slightly fewer PCNA-positive cells than Ki67-positive cells (53.91 ± 3.18 % vs. 68.50 ± 5.52 %, p = 0.0003), yet only a small fraction of tumor cells in DiFi xenografts were PCNA-positive (13.59 ± 1.48 % vs. 72.37 ± 12.64 %, p = 0.0003)." (PMID 23554961, 2013). "Interestingly, this group found that CD8+ T cells were correlated with higher tumor grade, hormone receptor negativity, and a basal phenotype, similar to our results with PCNA+ TAMs." (PMID 24205370, 2013). "Moreover, immunoreactivity for PCNA in EPO treated xenografts showed that tumor cells in peri-vessel areas displayed higher proliferation, which was indicated as increased PCNA staining." (PMID 22086127, 2012). "The results of the immunohistochemical analysis of PCNA-positive cells in tumor xenograft tissues indicated that the percentage of proliferating cells was significantly lower (60%, P<0.01) in tumor xenografts from GSPs-treated mice than in the tumor xenografts from the control mice." (PMID 23050025, 2012). "The proliferation index was defined as percent of tumor cells stained positively for PCNA." (PMID 23158838, 2012). "Analysis of the tissue biopsies from the xenograft SCID mice model would suggest that the combination can not only block the tumor cells from dividing as noted from the reduced expression of PCNA but also has a role to play in preventing the loss of differentiation of the tumor." (PMID 23342262, 2012). "Immunohistochemical studies showed regression of tumor cell proliferation as evident by Ki67 stained cells following 4a treatment, which was also consistent in case of western blot analysis, where we observed downregulation of PCNA after treatment with 4a in tumor lysate." (PMID 22970136, 2012). "It was observed that SD inhibited tumor multiplicity (50%–60% inhibition), tumor volume (70%–80% reduction) and the number of positive cells for the proliferation marker PCNA (16%, 40.7% and 53.6% for the 30 μg, 45 μg and 60 μg SD groups, respectively) as compared to the control (100%)." (PMID 23118725, 2012). "To investigate whether rapamycin alone or in combination with bortezomib decrease HCC tumor growth by inhibiting cell proliferation, we examined the number of PCNA-positive cells in HCCLM3-R tumors from mice with different treatments." (PMID 22559167, 2012). "Finally, we found that overexpression of CEACAM6 resulted in a modest increase in the expression of the proliferation marker, PCNA, when compared to control tumours." (PMID 23021083, 2012). "At the tumor periphery, the majority of proliferating cells were tumor cells, whereas the brain parenchyma surrounding the tumor contained several host (mouse) nestin-positive cells that expressed PCNA, suggesting that these host cell were proliferating." (PMID 22539956, 2012). "Immunohistochemical detection analysis of PCNA-positive cells in tumor xenograft tissues indicated that the percentage of proliferating cells was significantly lower in both the A549 (P<0.001) and H1299 (P<0.01) tumor xenografts from GSPs-treated mice than the xenograft tumors from the control mice." (PMID 22087318, 2011). "Indeed, that its is following a DNA hypomathylation strategy (inhibition of the Dnmt1 expression or treatment (5aza) or by comparing non tumor cells with tumor cells, the number of Dnmt1/PCNA interactions echoes the degree of DNA methylation." (PMID 21470401, 2011). "PCNA is an auxiliary protein of DNA polymerase whose level of synthesis correlates directly with rates of cellular proliferation and DNA synthesis; and it has been widely used as a marker to assess the mitotic index of tumour cells." (PMID 21283680, 2011).
tumor (continued). "SmoA1 +; Pten +/+ tumors displayed diffuse staining for PCNA throughout each tumor section." (PMID 20520772, 2010). "Therefore, we performed immunohistochemistry in tumor tissues to measure the expression of Ki67 and PCNA, and TUNEL assay to measure apoptosis." (PMID 21209944, 2010). "ApcMin/+/Faslpr mice had significantly more PCNA+ cells per tumor area than ApcMin/+ mice at most time points (p = 0.0014 at 8 weeks, p = 0.0038 at 16 weeks, p<0.0001 at 20 weeks and 30 weeks, n = 24–205 tumors for ApcMin/+/Faslpr and 18–58 tumors for ApcMin/+ in 4–5 mice per genotype)." (PMID 20140201, 2010). "Moreover, CTSB was identified in the cytoplasm of tumor cells showing different pattern from staining with anti-PCNA antibody in which PCNA was identified in nucleus." (PMID 20727192, 2010). "Proliferative activity of the tumor cells was assessed by anti-PCNA immunohistochemical staining." (PMID 21152068, 2010). "Immunohistochemical staining for PCNA on tumour bearing liver specimens was performed to determine if CGP42112A could inhibit proliferation of cancer cells in vivo." (PMID 20584290, 2010). "In addition, we determined the proliferation index of tumor cells by immunostaining tumor sections for proliferating cell nuclear antigen, a nuclear marker for proliferative cells." (PMID 20078855, 2010). "To determine whether the disruption of the Dnmt1/PCNA/UHRF1 interactions can promote the tumor transformation of Astro#40 and Ntv-a cells, we firstly investigated whether these cells acquired some hallmark of cancer after their transfection by the pUP plasmid." (PMID 20613874, 2010). "Secondly, residual hepatic VX2 carcinoma might facilitate rapid tumor progression through induction of overexpression of multiple molecular factors, such as PCNA, MMP-9, VEGF, HGF and IL-6." (PMID 20667141, 2010). "As induced and enhanced tumour growth may be the result of increasing proliferation or decreasing apoptosis, we examined the contribution of these two processes by PCNA and TUNEL immunostaining of tumours." (PMID 19401689, 2009). "It is plausible to use PCNA to reflect tumor phase, recurrence and malignancy and classification)." (PMID 18366613, 2008). "We used 8 factors namely FHIT, Ki-67, PCNA, abdominal mass, tumor size, decrease in bone content or fracture, blood cortisol level (4PM), blood ACTH level (8AM); as features in our system for differential diagnosis of hypercortisolism of adrenocortical diseases." (PMID 18366613, 2008). "PCNA is related to tumor classification, clinical phase, malignancy, metastasis and prognosis." (PMID 18366613, 2008). "PCNA is discovered recently as a candidate of tumor marker that reflects cell proliferation degree." (PMID 18366613, 2008). "Tumor behaviour and growth are considerably influenced by the expressions of two types of genes in the human genome: the cell proliferating genes (for instance, Ki-67 and PCNA) and tumor suppressor genes (for example FHIT)." (PMID 18366613, 2008). "Ki-67 is the more reliable indicator of the growth fraction of a tumor, largely because PCNA has a long half-life and may still be demonstrable in post-mitotic cells." (PMID 19690652, 2007). "In tumor samples PCNA and TUNEL index was significantly higher; than in benign diseases." (PMID 17697357, 2007). "Orthotopic tumor sections of mice bearing SN12C-VC and SN12C-VHL-KD tumors were stained using anti-Factor VIII-related antigen antibody, anti-PCNA antibody, or TUNEL method for the morphometric evaluation of tumor-associated vascular density, proliferation, or apoptosis, respectively." (PMID 17083723, 2006).
tumor (continued). "In addition, co-localization of both Perlecan and Sonic Hedgehog correlated with increased tumor cell proliferation as shown by Ki-67 (PCNA) staining." (PMID 16507112, 2006). "The cell cycle regulators, such as ER-α, the ER-α linked cyclin D1, cyclin-dependent kinase 4 (cdk4), and proliferating cell nuclear antigen (PCNA), all followed this pattern of high in tumor tissues, intermediate in tumor-surrounding livers and low in control liver." (PMID 16507464, 2006). "The tumour sections were stained for proliferating cell nuclear antigen (PCNA)." (PMID 11870550, 2002). "In addition, analysis of PCNA immunohistochemical staining revealed that Ang-1-overexpressing tumours had a significantly lower percentage of proliferating tumour cells in peritoneal metastases compared to control tumours (P<0.01)." (PMID 12402160, 2002). "In Ta-T1 tumours high fraction of PCNA/cyclin positive nuclei predicted metastasis (P = 0.019)." (PMID 1353364, 1992). "Then, the collected tumor tissues were tested and verified by IHC experiments, and the results exhibited that after circ_0008126 overexpression, the levels of vimentin, ki-67, and PCNA proteins had been down-regulated, while the levels of APC and E-cadherin proteins had been upregulated." (PMID 39858034, 2025). "Based on these data, it can be inferred that NaB may block the inhibition of NK cell effector functions in CRC by downregulating PCNA expression; disrupting its suppressive interaction with NK cell effectors; and reprogramming both the tumor cells and the tumor microenvironment." (PMID 39859117, 2025). "Interestingly, the labeling pattern of PCNA hints at a potential non-proliferative role in tumor-associated Sertoli cells." (PMID 40427255, 2025). "However, IL-15 can enhance NK-cell proliferation and cytotoxicity, while proliferating cell nuclear antigen (PCNA) overexpression in GBM may facilitate NK cell targeting of tumor cells." (PMID 40075663, 2025). "In solid tumors with elevated proliferating cell nuclear antigen (PCNA) levels and reduced phosphatase and tensin homolog deleted on chromosome ten (PTEN), androgen receptor, caspase-3, and Bcl-2-associated X protein (Bax) levels, high IL-6 amounts contribute to tumor development." (PMID 40420174, 2025). "Additionally, the OGFRP1 inhibition group exhibited decreased expression of PCNA in tumor tissues." (PMID 39352634, 2025). "In addition, the tumor size was significantly reduced in the combination group, and the expression of the apoptosis marker Cleaved Caspase-3 was up-regulated, and the proliferation markers Ki67/PCNA were down-regulated." (PMID 40919243, 2025). "Importantly, PCNA downregulation may also mitigate immune evasion, as tumor-cell PCNA has been shown to bind the NKp44 receptor on NK cells, thereby suppressing their cytotoxic function." (PMID 40430573, 2025). "Interestingly, a significant increase in the percentage of CC3-positive tumour cells was observed following olaparib treatment, which was accompanied by a significant decrease in the percentage of PCNA-positive tumour cells, suggesting the CU-PC01 PDX model is sensitive to PARP inhibition ex vivo." (PMID 38667288, 2024). "Concordantly, while sunitinib treatment could effectively inhibit tumor growth in the control groups, the PCIF1 knockdown group exhibited a superior response to treatment reflected in tumor weight and size, accompanied by a significantly decreased staining of PCNA and angiogenesis marker CD31." (PMID 39422663, 2024). "Similarly, the expression of genes for cell differentiation (CAV1 for caveolin-1) and cell proliferation (MKI67 for marker of proliferation Ki-67 and PCNA for proliferating cell nuclear antigen) were down- and upregulated, respectively, in tumor samples (adjusted p value < 0.01)." (PMID 39062740, 2024).
tumor (continued). "Besides, spheroid cells-generated tumors showed the cellular robust activity compared with parent cells tumor as proliferative-related protein PCNA, angiogenesis-related protein VEGF, CSC-related protein CD133 and HIF-1α displayed significantly increased expressions in spheroid cells induced tumors." (PMID 37143105, 2023). "In addition, the expression of PCNA in tumor tissue was also reduced." (PMID 37740183, 2023). "Importantly, a novel cancer-associated PCNA isoform (caPCNA) was discovered to be the predominant PCNA isoform expressed in a broad range of cancer cells and tumor tissues but was not highly expressed in non-malignant cells." (PMID 37510250, 2023). "Therefore, a significant increase in PCNA-positive tumor cells in the H group may also result from the decrease in immune surveillance by the activated TGF-β1." (PMID 37175975, 2023). "Tumour tissue lysate examination revealed a decrease in the expression levels of Wnt target genes, localization of β-catenin and expression of proliferative markers such as PCNA (proliferating cell nuclear antigen), osteoponin and Ki-67 protein (cell proliferation marker)." (PMID 38067491, 2023). "Moreover, immunohistochemical staining showed that tumor with Ki67 exon 7 knockdown showed reduced expression of PCNA (cell proliferation marker), Cyclin D1 (cell cycle marker), and N-cadherin (epithelial to mesenchymal transition, EMT, marker), but increased expression of E-cadherin (EMT marker)." (PMID 36835286, 2023). "In addition, tumor HE staining and immunohistochemical indices (PCNA, Ki-67, Cleaved-caspase-3, Bcl-2) confirmed that Arte could be a relatively effective sensitizer and enhance 5-FU antitumor activity." (PMID 37498338, 2023). "Our research utilized immunohistochemistry to reveal that the combined treatment of GTW and DDP can significantly reduce PCNA expression in tumor tissues compared to DDP treatment alone, indicating that the combination of GTW and DDP may inhibit tumor proliferation." (PMID 37818040, 2023). "Moreover, the expression of PCNA in tumor tissues was detected by immunohistochemistry (IHC), and that in the combined treatment group was also profoundly decreased, which further indicated the strongest anti-tumor effect." (PMID 37361567, 2023). "Owing to the small size of tumor tissue in the sh-circMBOAT2 group, we took material from the other 3 groups and performed IHC staining, which revealed an increased proportion of proliferating cells (Ki67+ and PCNA+) in the upregulated expression of circMBOAT2 group compared with the control group." (PMID 36635270, 2023). "By flow cytometry, we did not observe membrane-associated PCNA expression in the cells derived from patient #2’s tumor; this is associated with lack of binding to the tumor that is probably imperative to mediate peptide penetration into the tumor cell." (PMID 36430528, 2022). "Moreover, the tumor cell growth index was measured by PCNA IHC staining." (PMID 36341459, 2022). "Consequently, Ki67 and PCNA could reflect the proliferative activity of tumor cells, suggesting their potential status as prognostic indicators." (PMID 35978996, 2022). "In addition to scattered PCNA-positive cells distributed throughout the neoplasia, we found distinct foci of strongly proliferating cells indicating that tumor heterogeneity may be involved in progression of HLN." (PMID 36209041, 2022). "Furthermore, L. plantarum-12 oral administration significantly ameliorated the colon injury of the AOM/DSS-treated mice by enhancing colonic tight junction protein level and promoting tumor cells death via down-regulating PCNA (proliferating cell nuclear antigen) and up-regulating pro-apoptotic Bax." (PMID 35565884, 2022). "PCNA is a nuclear protein involved in regulating DNA replication, DNA repair, and cell cycle progression; it may be overexpressed in cancer cells, promoting tumor survival and malignancy." (PMID 35757695, 2022).
tumor (continued). "To assess the proliferative activity of tumor cells and observe whether the inhibitory effect of grain-sized moxibustion combined with CTX on tumor growth in mice is related to the proliferation genes Ki67 and PCNA, we performed immunohistochemical analysis of tumor proliferation activity." (PMID 35978996, 2022). "Since EGCG treatment resulted in proliferating cell nuclear antigen (PCNA) downregulation and activation of CCN5 in tumor tissues, tumor growth inhibition could be mediated via suppressing PCNA, a protein that actively participates in cell cycle regulation and apoptosis, and CCN5 activation." (PMID 33745223, 2021). "Particularly, the regions between the fat and tumor tissues were the main target areas for immune cell infiltration, indicating the immune cell-mediated interaction between the adipocytes and cancer cells followed by the higher potentiation of PCNA and F4/80-positive cells under obese conditions." (PMID 34638514, 2021). "Therefore, we analyzed tumor cell proliferation by PCNA immunohistochemical staining." (PMID 33995664, 2021). "Moreover, oAd/IL12/GM-RLX plus αPD-1-cotreated tumors showed a much lower density of proliferating tumor cells (PCNA-positive) than did tumors treated with monotherapy, suggesting that the combination of oncolytic Ad with αPD-1 inhibits tumor cell proliferation more effectively than monotherapy can." (PMID 32753544, 2020). "In addition, cells immunoreactive for the proliferation marker PCNA were significantly decreased in the treated tumor masses compared with the normal saline-treated tumor masses, and anlotinib combined with chemoradiation treatment resulted in the lowest PCNA levels." (PMID 32754439, 2020). "In addition, concerning the proliferation marker PCNA, we evidenced a reduced expression in metastatic nodules in 4T1 M. U-care mice, thus highlighting an evident inhibitory effect of the MM blend on proliferation activity in tumor cells." (PMID 33218180, 2020). "In addition, based on the notion that proliferative activity of cancer cells is also a crucial prognostic marker in the tumor diagnosis, we investigated the role of Proliferating Cell Nuclear Antigen (PCNA), being a pivotal protein directly related to the degrees of tumor malignancy and diagnosis." (PMID 33218180, 2020). "Further, in parallel we investigated PCNA expression pathway, based on the great interest on the pivotal role of PCNA in cancer cells proliferation, also taking into consideration that PCNA modifications may determine both tumor progression as well as the outcome of anticancer treatment." (PMID 33218180, 2020). "Furthermore, PCNA expression levels were increased in the groups containing Nodal-overexpressing tumor cells combined with 3T3 cells, which were different from the normal or Nodal-silenced tumor cells combined with 3T3 groups." (PMID 31167491, 2019). "GO and KEGG pathway analysis, as well as experimental observation showed that CBX3 may be associated with cell cycle transition of PAAD cells, and cyclin-dependent kinase 1 (CDK1) and proliferating cell nuclear antigen (PCNA) may mediate the tumor-promoting action of CBX3." (PMID 29903985, 2018). "These peptides/proteins play an important role in regulating tumor energy metabolism, epithelial to mesenchymal transition of cancer cells, the stability of the c-Myc oncoprotein, and the ubiquitination and degradation of proliferating cell nuclear antigen (PCNA)." (PMID 30483132, 2018).